CCL5 (C-C motif chemokine ligand 5)
Diseases named in the same sentence as CCL5 in open-access papers (continued):
Sharing a sentence is not in itself a finding about the gene and the disease.
dengue (42 papers, 2007 to 2025). "Production of RANTES/CCL5, a chemokine associated with altered vascular permeability in dengue, was found mainly in endothelial and microglial cells." (PMID 32486462, 2020). "We used the KU812 cell line to demonstrate for the first time that anti-dengue antibodies enhanced infectious Zika virus replication in a mast cell model and specifically increased CCL5, CXCL10, and IL-1β, while also impairing granzyme B secretion." (PMID 35862953, 2022). "At this point in the study, the authors suggested a relationship between low circulating levels of CCL5 and worse clinical signs of dengue." (PMID 35631030, 2022). "Together, the studies indicate that high tissue expression of CCL5 and low circulating levels of CCL5 would be involved in cell migration to specific sites in dengue." (PMID 35631030, 2022). "In cases of dengue death, our group demonstrated an increase in the frequency of CCL5+ cells in the patients’ liver, but lower circulating levels of CCL5 in the patients compared to healthy controls." (PMID 35631030, 2022). "Another study also demonstrated an increase in the frequency of CCL5+ cells and viral antigens in liver, lung, and kidney tissues from dengue deaths." (PMID 35631030, 2022). "An increase in the expression of CCR5 in T cells and a decrease in CCL5 plasma levels, in patients in the acute phase of dengue, have already been demonstrated by our group." (PMID 33525328, 2021). "In wild-type mice, mast cells responding to dengue virus infection upregulated chemokine expression (RANTES/CCL5, SDF-1/CXCL12, and fractalkine/CX3CL1), and mediated recruitment of NKT cells (CD3+NK1.1+) into the skin at sites of dengue virus infection." (PMID 26074921, 2015). "IFN signatures and CCL5 were previously found to be up-regulated in microarrays of dengue patients' PBMCs and in the serum, whereby higher expression seemed to be associated with less severe disease." (PMID 25474532, 2014). "Transcription of IFN-β, STAT-1 and CCL5 was significantly up-regulated in all APC subsets upon dengue virus infection." (PMID 25474532, 2014). "Circulating levels of CCL4 and CCL5 in dengue patients are positively correlated with good prognosis." (PMID 22479521, 2012). "In support to these events there is evidence that evaluation of liver tissue specimens from four dengue fatal cases indicates the increased CCL5/RANTES expression in resident cells during dengue infection." (PMID 22815692, 2012). "Finally, liver from dengue fatal patients showed increased number of cells expressing CCL5/RANTES in three out of four cases compared to three death from a non-dengue patient." (PMID 22815692, 2012). "The CCR5 expression would be promoting an enhanced T cell recruitment into liver, a hypothesis that is corroborated by the CCL5/RANTES increase detected in hepatic tissue from dengue fatal cases." (PMID 22815692, 2012). "Mice infected with DENV and treated with Met-RANTES, a potent CCR5 inhibitor, were found to have lower viral load and increased survival, thus indicating that inhibition of the CCL5/RANTES interaction through CCR5 may be an important therapeutic target in dengue." (PMID 33525328, 2021). "In addition, we found a high frequency of CCL5+ cells in the liver tissue of fatal dengue cases." (PMID 33525328, 2021). "Further assessment of host factors revealed that cytokines such as CCL2, CCL5, CCL20 and CXCL1, as well as adhesion molecule ICAM-1, that are involved in leukocytes infiltration were expressed higher in dengue patients in comparison to healthy individuals." (PMID 32764789, 2020). "Even though the degree of thrombocytopenia and platelet activation were similar between dengue-infected and HIV plus dengue-coinfected patients, plasma levels of the platelet-derived chemokines RANTES/CCL5 and PF4/CXCL4 were lower in coinfection." (PMID 31068600, 2019).
dengue (continued). "We then quantified the levels of the chomokines RANTES/CCL5 and PF4/CXCL4 secreted ex vivo by platelets isolated from dengue-infected or HIV plus dengue-coinfected patients." (PMID 31068600, 2019). "It was found that for CBMCs, polyI:C and antibody-enhanced dengue virus infection were able to induce significant levels of CCL4, CCL5 and CXCL10." (PMID 22479521, 2012). "A study has suggested that low levels of CCL5 and high levels of CXCL8 during early dengue infection could serve as a marker for severe dengue disease." (PMID 37644081, 2023). "Our results demonstrate increased levels of TNF-α and MCP-1/CCL2 in patients that evolved with either mild dengue or warning signs and severe dengue syndromes, while higher levels of IFN-ɣ, RANTES/CCL5 and IL-1β were observed only in plasma from patients presenting warning signs and severe dengue." (PMID 36569864, 2022). "The data demonstrate that IFN-γ and CCL5/RANTES levels did not differentiate dengue groups and healthy donors." (PMID 35631030, 2022). "Moreover, we observed that fatal dengue cases presented relevant local pro-inflammatory responses in their peripheral organs, with the participation of IFN-γ, TNF-α and RANTES/CCL5-producing cells." (PMID 32486462, 2020). "DENV-infected people had high levels of CCL5 and chitinase-3-like 1 during acute infection, and livers from fatal dengue patients had increased CCL5 compared to non-dengue control." (PMID 32854687, 2020). "Even though most of the chemokines were present at similar levels in samples from dengue infected and HIV plus dengue coinfected patients, the platelet-derived chemokines PF4/CXCL4 and RANTES/CCL5 were reduced in patients coinfected with HIV when compared to patients infected with DENV only." (PMID 31068600, 2019). "RANTES, also known as CCL5, is an early expressed chemokine induced by pattern recognition receptors, but can also be induced by TNF-α and IFN-γ at late stages of infection, that is the case of a terminal dengue situation." (PMID 28006034, 2016). "The quantification of positive cells showed an increase (ranging from 1.9 to 5.5 fold) in the number of cells expressing CCL5/RANTES on the 50 fields in four dengue fatal cases comparing to data obtained from three non-DENV fatal cases." (PMID 22815692, 2012). "Mast cells responded to antibody-enhanced dengue virus infection or polyinosiniċpolycytidylic acid treatment with the production of type I interferons and the rapid and potent production of chemokines including CCL4, CCL5 and CXCL10." (PMID 22479521, 2012). "However, like HMC-1 cells, KU812 cells did produce CCL4, CCL5 and CXCL10 in response to antibody-enhanced dengue virus infection." (PMID 22479521, 2012). "While the influence of CCL4 and CCL5 on the overall immune response to dengue virus infection is not well studied, clinically these chemokines are decreased in serum of dengue hemorrhagic fever patients, and therefore their levels may serve as good prognostic factors for disease outcome." (PMID 22479521, 2012). "Platelets isolated in the acute phase from dengue-infected patients, but not platelets from HIV plus dengue-coinfected patients, released higher levels of PF4/CXCL4 and RANTES/CCL5 when incubated ex vivo compared to platelets from the same patients collected and examined at the recovery." (PMID 31068600, 2019). "However, when platelets isolated from patients were incubated ex vivo, platelets from coinfected patients secreted lower levels of RANTES/CCL5 and PF4/CXCL4, but not IL-1β, compared to patients with dengue without HIV coinfection." (PMID 31068600, 2019).
breast tumor (41 papers, 2009 to 2025). "One report noted coordinated over-expression of TNF-α, IL-1β, and chemokines (CCL2, CCL5) in breast tumors, which was associated with epithelial–mesenchymal transition (EMT) and invasive behavior." (PMID 41007766, 2025). "High expression of CCL5 in breast tumors was significantly associated with an increased OVS in all BC patients, but particularly in TNBC/Basal-like patients." (PMID 31921621, 2019). "CCL5 might play an antitumor role as it is negatively related to the number of tumor associated macrophages, which are the major components of the breast tumor stroma and contribute to tumor growth and development." (PMID 36685922, 2022). "Further support for CCL5 involvement in metastasis was obtained in murine breast tumor models, where enhanced CCL5 expression correlated with lung and liver metastases, which were effectively inhibited by blocking CCL5 signaling." (PMID 39566333, 2025). "Altogether, these data supported the lineage relationship between tumor-infiltrating CD16+ and CD16- CD103+ NK cells in human breast tumors, both subsets capable of CCL5/IFN-ɣ production." (PMID 38167224, 2024). "Supporting this observation, it was shown that DNA repair-deficient breast tumors were associated with CD4+ and CD8+ lymphocyte infiltration and that cells from these DNA repair-deficient breast tumors expressed the chemokines CXCL10 and CCL5 more strongly." (PMID 37420037, 2023). "CCL5 mediates breast tumor progression and recurrence by interacting with the CCR3 axis, recruiting macrophages and regulating the CD4+/CD8+, CCR5+/CD4+ or Treg/CCR5+ cell ratios." (PMID 37051596, 2023). "When we examined the expression of these CCL5-regulated cytokines across breast tumors, we found that high expression of cytokines and chemokines clustered with high expression of CCL5 in triple-negative/basal-like breast tumors." (PMID 34298673, 2021). "We observed that CCL5 protein production was significantly increased in human fibroblasts exposed to breast tumor cell factors compared to untreated fibroblasts." (PMID 33868996, 2021). "In conclusion, we provide evidence that MEKK1-dependent CCL5 expression in mammary fibroblasts can induce a functional response in breast tumor cells that is a key requirement for breast tumor metastasis to occur." (PMID 33868996, 2021). "Although reduced in MEKK1 knockout cells, CCL5 expression was induced significantly by breast tumor cell-conditioned media in both MEKK1+/+ and MEKK1−/− fibroblasts, indicating that control of induced CCL5 expression is at least partly independent of MEKK1." (PMID 33868996, 2021). "Previous research also found that MDSCs from CCL5-knockout mice with breast tumors expressed less NOS2 and S100A8/9 and showed an immune-stimulatory phenotype." (PMID 34566958, 2021). "CCL5 can induce breast tumor cell migration through binding and activation of CCR5, and an inhibitory mutant CCL5 (met-RANTES) inhibits breast tumor growth and migration." (PMID 33868996, 2021). "Analysis of the expression of CCL5-regulated cytokines in patient breast tumors revealed ~75 percent were highly correlated with CCL5 expression in TCGA." (PMID 34298673, 2021). "In the same spirit, CCL5 produced by MSCs has acted on CCR5-expressing breast tumor cells, leading to the release of CSF-1 and then to increased accumulation of macrophages and MDSCs in tumors." (PMID 32582148, 2020). "This was evidenced by a CCL2-promoted formation of primary and secondary tumor spheroids that contained more self-renewing CSCs, and by the fact that stimulation of breast tumor cells with CCL5 increased the CD44+/CD24− sub-population." (PMID 32582148, 2020). "For example, osteopontin was found to be a key factor released by breast tumor cells, binding αVβ3 integrins expressed by MSCs and then giving rise to elevated levels of CCL5 production." (PMID 32582148, 2020).
breast tumor (continued). "Parallel studies on CCL5 demonstrated its ability to induce small increases in breast tumor cell proliferation; in one of the research systems, such CCL5 activity was mediated by CCR5-dependent mTOR activation." (PMID 32582148, 2020). "Cooperativity of CCL5 with IL-6 was also noted when CM of MSCs promoted breast tumor cell migration." (PMID 32582148, 2020). "We then wanted to determine if CCL5 expression was elevated in human residual breast tumors following treatment." (PMID 30990165, 2019). "Paracrine activities of intra-tumoral CCL5 through its cognate receptor CCR5 are reported to promote breast tumor progression, and LN and thoracic metastasis." (PMID 31705019, 2019). "In one study, these inflammatory cytokines alongside with inflammatory chemokines; CCL2 and CCL5 are expressed in a coordinated fashion which provides a combined role of the mediators to supports the growth and progression of breast tumor." (PMID 27558166, 2016). "The chemokine (C-C motif) ligand 5 (CCL5; aka RANTES) is an 8kDa peptide that is up-regulated in breast tumors, and has been associated with metastatic spread." (PMID 27863423, 2016). "Certainly, published reports of a role for CCR5 in increased breast tumour metastasis and invasion align with these findings of CCL5 activating CCR5 to invoke a cascade of signalling pathways increasing the metabolic capacity of cells to enable these events." (PMID 27335323, 2016). "In previous work, CCL5/CCR5 antagonism has been shown to inhibit breast tumor metastasis, leading to tumors that are pale and necrotic." (PMID 27863423, 2016). "This lack of coordination between CCL2 & CCL5 and TNFα & IL-1β in this sub-population is intriguing mainly because TNFα and IL-1β were found to stimulate the release of CCL2 and CCL5 by breast tumor cells." (PMID 21486440, 2011). "While the expression of CCL2, CCL5, TNFα or IL-1β was only minimally detected in infiltrating leukocytes of all groups of patients, the four factors were clearly observed in breast tumor cells, with mainly a cytoplasmic staining pattern." (PMID 21486440, 2011). "During the in vitro conversion process of mesenchymal stromal cells in cancer-associated fibroblast by breast tumor cell (MDA-MB-231 and MCF-7)-conditioned media, TNF-alpha stimulation is responsible for the chemokines released (CCL2, CXCL8, and CCL5) by the tumor stromal cells." (PMID 37681908, 2023). "CCL5 expression was also elevated in human residual breast tumors following treatment." (PMID 37759462, 2023). "The abundance of mature neutrophils in primary tumors of 4T1 breast tumor mouse models was influenced by host CCL5, produced by myeloid cells in a CCR5-CCL5 autocrine manner, rather than by tumor-derived CCL5, resulting in the generation of immunosuppressive immature Ly6G+ myeloid cells." (PMID 35328639, 2022). "Future studies should reveal whether primary breast tumors directly produce CCL5 to elicit the Th2 immune response or promote the generation of CCL5 by other tissues or cells." (PMID 34707103, 2021). "To determine whether breast tumor-derived soluble factors can induce CCL5 protein expression in human mammary fibroblasts, we measured the CCL5 protein produced by HTB-125 human mammary fibroblasts exposed to MDA-MB 231 cell-conditioned media." (PMID 33868996, 2021). "Also, the study by Weinberg and colleagues demonstrated that CCL5 released by MSCs has acted through CCR5 to promote breast tumor cell migration, invasion and metastasis in animal studies." (PMID 32582148, 2020). "We addressed this hypothesis by assessing the correlation between CCL5 expression in breast tumors and disease survival using the TCGA dataset." (PMID 31921621, 2019). "Therefore, to determine the specific contribution of cancer cell derived CCL5 to angiogenesis we stably suppressed CCL5 in immune competent breast tumor models." (PMID 27863423, 2016).
breast tumor (continued). "Although work from our laboratory and others has shown that CCR5 is expressed by EPCs the mechanism of CCL5/CCR5 signaling in EPC mediated breast tumor neovascularization remains unclear." (PMID 27863423, 2016). "Such a cross-talk may lead to up-regulated expression of CCL2 and CCL5 in tumors expressing TNFα and/or IL-1β, thus possibly leading to increased tumor-supporting activities of the two chemokines in breast tumors (see Discussion, below)." (PMID 21486440, 2011). "The inter-connection between CCL2 & CCL5 and TNFα & IL-1β in the immune setting suggests that similar interactions exist between these chemokines and cytokines also within the inflammatory context of breast tumors." (PMID 21486440, 2011). "Indeed, our findings and published studies indicate that TNFα and IL-1β up-regulate the release of CCL2 and CCL5 by breast tumor cells." (PMID 21486440, 2011). "A recent study also showed that overexpression of TILRR in BT474, a human breast tumor cell line, significantly potentiates the expression of immune and inflammation-associated genes, including IL-6, IL-8/CXCL8, IP-10 (interferon gamma-induced protein 10)/CXCL10, MCP-1/CCL2, and RANTES/CCL5." (PMID 34360591, 2021). "In human breast tumors, the CD16 and CD103 markers identified lineage-related NK cell subpopulations capable of producing CCL5 and IFN-ɣ, which correlated with tissue-resident CD8+ T cells." (PMID 38167224, 2024). "Mechanistic studies in in vitro and in vivo ADCC models indicate the importance of NK cells for the initial production of CCL5/IFN-ɣ, subsequently resulting in CXCL9/10 production by bystander breast tumor cells, during anti-HER2 antibody treatment." (PMID 38167224, 2024). "CCL5, also known as Regulated upon Activation, Normal T Cell Expressed and Secreted (RANTES), is another well-known factor that recruits TAMs to the breast tumor." (PMID 33968034, 2021). "Together, our mRNA and protein data indicate that soluble factors produced by breast tumor cells can induce CCL5 protein production in non-tumor mammary stroma cells." (PMID 33868996, 2021). "Monocyte chemoattractants CCL5 and CCL2 secreted by breast tumor cells may induce monocyte infiltration to the microenvironment of breast tumors." (PMID 22408433, 2012). "Also, preliminary analyses that we have performed indicated that CCL2 and CCL5 were not capable of inducing EMT-related processes in the breast tumor cells (data not shown)." (PMID 21486440, 2011). "The results showed that CCL5 and IDH2 were not significantly differentially methylated in BRCA, while CCR7, EZR, IL8, and IL2RG were hypermethylated in normal tissues, and FLT3, MAPK10, and MMP9 were hypermethylated in breast tumor tissues." (PMID 38438469, 2024).